SUCO (SUN domain containing ossification factor)
Description:
Required for bone modeling during late embryogenesis. Regulates type I collagen synthesis in osteoblasts during their postnatal maturation (By similarity).
Synonyms: C1orf9; CH1; OPT; SLP1
Tractability: Antibody: UniProt predicts a signal peptide or a membrane-spanning region. PROTAC: its protein half-life has been measured.
Gene: Protein-coding gene on chromosome 1 (172,532,349 to 172,611,833, forward strand). Ensembl gene ENSG00000094975.
Subcellular location: Rough endoplasmic reticulum membrane
Subcellular location (Human Protein Atlas): Cytosol; Nucleoli fibrillar center
Gene Ontology:
Biological process: positive regulation of collagen biosynthetic process; positive regulation of osteoblast differentiation; regulation of bone remodeling
Cellular component: membrane; rough endoplasmic reticulum; rough endoplasmic reticulum membrane
Genetic constraint (gnomAD): Loss-of-function variants: 26 observed, 82.99 expected, observed/expected ratio (o/e) 0.31, 90% interval 0.23 to 0.44. The upper end of that interval is the gene's LOEUF score, 0.44, which puts it in group 1 of 6, group 1 being the genes least tolerant of losing a copy. Missense variants: 965 observed, 1,058.8 expected, observed/expected ratio (o/e) 0.91, 90% interval 0.86 to 0.96. Synonymous variants: 337 observed, 374.18 expected, observed/expected ratio (o/e) 0.9, 90% interval 0.82 to 0.99.
Homologues: Orthologues: macaque SUCO (98% identical), chimpanzee SUCO (95% identical), dog SUCO (90% identical), rabbit SUCO (88% identical), pig SUCO (87% identical), guinea pig SUCO (87% identical), mouse Suco (86% identical), rat Suco (85% identical), tropical clawed frog suco (59% identical), zebrafish suco (46% identical), Drosophila melanogaster CG31678 (22% identical), Caenorhabditis elegans suco-1 (16% identical).
Diseases named in the same sentence as SUCO in open-access papers:
SUCO is named in the same sentence as 22 diseases in open-access papers, as found by Europe PMC text mining. Sharing a sentence is not in itself a finding about the gene and the disease. The quoted sentences say what the papers report.
hepatocellular carcinoma (3 papers, 2021 to 2022). A malignant tumor that arises from hepatocytes. "SUCO is overexpressed in hepatocellular carcinoma (HCC) tissues, andhigh SUCO expression is significantly correlated with a low overall survival rate in HCC patients." (PMID 36437242, 2022). "SUCO was found to be upregulated in hepatocellular carcinoma and may be targeted by miR-497." (PMID 35211507, 2021). "Based on these findings, a potential miR-497-mRNA or miR-1246-mRNA regulatory network can be established, namely, miR-497-ARL2/UBE2Q1/PHF19/APLN/CHEK1/CASK/SUCO/CCNE1/KIF23, or miR-1246-AUTS2/SLAIN1, which contributes to the occurrence and development of hepatocellular carcinoma." (PMID 34163524, 2021).
osteogenesis imperfecta (2 papers, 2024 to 2025). Osteogenesis imperfecta (OI) comprises a heterogeneous group of genetic disorders characterized by increased bone fragility, low bone mass, and susceptibility to bone fractures with variable severity. "We identified a homozygous missense variant (p.R942T) in SUCO predicted to be deleterious in family F804, where two affected siblings presented with symptoms of spastic CP together with an osteogenesis imperfecta phenotype." (PMID 41282771, 2025). "SUCO (SUN domain-containing ossification factor) has been associated with skeletal dysplasia, osteopenia, and osteogenesis imperfecta." (PMID 38396997, 2024).
breast carcinoma (1 paper, 2021). "SUCO has 10 main isoforms (transcripts), and they showed distinct expression distributions in breast cancer." (PMID 35211507, 2021). "We then analyzed the isoform expression data of the SUCO gene in breast cancer based on the GEPIA2 database." (PMID 35211507, 2021). "TCGA data were used to test whether the predicted miRNAs and mRNAs (and the host gene SUCO) for circ_0000160 are deregulated in breast cancers with lymph node metastasis." (PMID 35211507, 2021). "Overall, SUCO was upregulated in breast cancer tissues compared with normal breast tissues." (PMID 35211507, 2021). "Our data showed that circ_0000160 was downregulated, while the host gene SUCO showed no significant change in breast cancer with lymph node metastasis compared with those without lymph node metastasis." (PMID 35211507, 2021). "However, the host gene SUCO and the analyzed miRNAs (data not shown) showed no obvious difference in breast cancer with lymph node metastasis and those without lymph node metastasis." (PMID 35211507, 2021).
osteochondrodysplasia (1 paper, 2023). A term referring to disorders characterized by abnormalities in the development of bones and cartilage. "Although loss‐of‐function mutations in TAPT1, SUCO and P4HB in humans all result in osteochondrodysplasia‐like phenotypes, the homologs of these genes in lower organisms lead to unrelated phenotypes when absent." (PMID 36652330, 2023).
tumor (10 papers, 2016 to 2025). "The results of this study illustrate that SUCO may be a tumour suppressor gene in CM, suggesting that SUCO plays different roles in the occurrence and development of different tumours." (PMID 36437242, 2022).
cancer (4 papers, 2021 to 2025). A tumor composed of atypical neoplastic, often pleomorphic cells that invade other tissues. "The host gene SUCO (the SUN domain containing the ossification factor) has rarely been investigated in human cancers." (PMID 35211507, 2021).
skeletal dysplasia (2 papers, 2023 to 2024). Any Mendelian diseases that affects growth and development of the skeleton. "Notably, mutations in SUCO and P4HB have been linked to skeletal dysplasia in humans, which aligns with the TAPT1 loss‐of‐function clinical presentation." (PMID 36652330, 2023).
SUCO also shares sentences with these, for which no sentence is quoted: infection (4 papers); co-infection (2); heavy chain disease (2); Allergy (1); autism (1); bone disorder (1); cholesteatoma (1); colorectal cancer (1); COVID-19 (1); liver cancer (1); lymph node metastasis (1); Osteopenia (1); ovarian carcinoma (1); prostate carcinoma (1); schizophrenia (1).